PRL (prolactin)
Diseases named in the same sentence as PRL in open-access papers (continued):
Sharing a sentence is not in itself a finding about the gene and the disease.
Infertility (continued). "This case highlights the possibility of the occurrence of a normal pregnancy during a long period of amenorrhea induced by a microprolactinoma with a high level of serum PRL, even if DA fails to correct infertility." (PMID 36556282, 2022). "The infertile non-PCOS womenwith higher levels of prolactin had lower dyspareunia andthose with higher LH had lower total FSFI and lubricationproblems, while the higher the central obesity the highertheir arousal problems." (PMID 33497050, 2021). "More recently, serum PRL levels have been reported significantly higher in infertile patients with endometriosis as compared to those without endometriosis, and PRL has been proposed as a biomarker for endometriosis diagnosis and severity." (PMID 33162942, 2020). "Patients with PRL excess, either tumoral and non-tumoral, experience the disruption of eugonadic state leading to hypogonadism and infertility." (PMID 33162942, 2020). "Moreover, elevated serum levels of LH, FSH andPRL were significantly associated with azoospermia, oligozoospermia and asthenozoospermia while in normozoospermic infertile individuals serum FSH and PRL were elevated." (PMID 32405170, 2020). "WHtR had a significant negative partial correlation with prolactin in both primary (R = − 0.226) and secondary (R = − 0.256) infertility." (PMID 31455408, 2019). "Binita investigated 160 women with primary infertility and found a slightly higher prevalence of hypothyroidism in the infertile group in comparison with that of the general population, also there was a positive correlation between serum TSH and prolactin levels in the infertile subjects." (PMID 30705778, 2019). "Among patients with tubal cause of infertility, a significant partial negative correlation was observed between WC (R = − 0.53), WHtR (R = − 0.55), WHR (R = − 0.41), BAI (R = − 0.44) and prolactin." (PMID 31455408, 2019). "Waist circumference (WC) and waist-to-height ratio (WHtR) showed significant negative partial correlation with prolactin in both primary and secondary infertile women." (PMID 31455408, 2019). "In this population of infertile patients, hormonal values were reported as follows (mean ± SD): LH 4.2 ± 3.6 mUI/mL; FSH 7.9 ± 3.2 mUI/mL; T 4.6 ± 1.5 ng/mL; E2 27.2 ± 5.4 pg/mL; DHT 0.21 ± 0.2 ng/mL; SHBG 35.7 ± 5.8 nmol/L, PRL 11.5 ± 3.4 ng/ml." (PMID 29410650, 2017). "Despite the reproductive defects exhibited by mutant females, PRL-/- male mice are fully fertile, and most PRLR-/- males are fertile, which demonstrates that the infertility in knockout females is caused by the lack of prolactin’s luteinizing effects." (PMID 27901187, 2016). "One study reported an elevation of baseline serum PRL in infertile and fertile women with minimal and mild endometriosis as compared with both fertile and infertile patients without endometriosis." (PMID 26000006, 2015). "There have been several studies in the literature measuring basal serum PRL levels in infertile patients with or without endometriosis." (PMID 26000006, 2015). "The PRL levels were significantly higher in infertile women with endometriosis vs. the infertile women without endometriosis (p=0.004)." (PMID 26000006, 2015). "Furthermore, with the exception of one study performed 30 years ago, there have been no studies that have included circadian prolactin variation (i.e., nocturnal peak) in patients with endometriosis-related infertility." (PMID 39407928, 2024). "In males, prolactin inhibits the hypothalamic secretion of GnRH and, consequently, inhibits the pulsatile release of FSH and LH in the pituitary gland, reducing testicular testosterone, resulting in alterations in spermatogenesis, poor sperm quality, and infertility." (PMID 37888562, 2023). "However, no guidelines address the aspect of optimal prolactin levels during infertility treatment for optimal outcomes." (PMID 36678618, 2023).
Infertility (continued). "However, age, BMI, duration of infertility, estradiol levels, total testosterone, prolactin, TSH, and SHBG concentrations were not significantly different between normo-androgenic PCOS and NOR patients." (PMID 33992122, 2021). "Also a significant negative partial correlation was observed between BMI and prolactin in secondary infertile women only." (PMID 31455408, 2019). "In infertile subjects,treatment with the herbal preparation Withaniasomnifera effectively reduced oxidative stress andimproved the levels of semen quality indicators oftotal testosterone (T), luteinizing hormone (LH),follicle-stimulating hormone (FSH) and prolactin(PRL)." (PMID 24520443, 2013). "More recently, we studied a group of unselected infertile patients (n = 100; divided into 3 subgroups: VAR, infections, other etiologies) and 31 fertile men, also correlating Lag values (TAC) with circulating hormones: gonadotropins, testosterone, estradiol, fT3, fT4, TSH, and prolactin (PRL)." (PMID 21915179, 2012). "This hypothesis is supported by the study on endometrial samples collected by hysteroscopy in the late luteal phase in patients with unexplained infertility and repeated miscarriages, which reported the lack of endometrial prolactin expression during the “implantation window’’." (PMID 39407928, 2024). "The prolactin levels in the plasma of infertile women with EMS were significantly higher than those without EMS, and the prolactin levels in stage III/IV were higher than in stage I/II EMS patients." (PMID 41301454, 2025). "Age, BMI, history of adverse pregnancy, Infertility years history of assisted reproduction, FSH, E2, AMH, PRL, P, number of eggs harvested were not significantly different between the two groups." (PMID 38053145, 2023). "In the new cohort, the age, BMI, duration of infertility and the levels of FSH, E2, P, PRL, LH and T, all had no significant statistic differences." (PMID 38155160, 2023). "Prolactin is a probable prognostic biomarkerto detect endometriosis stages III/IV vs. I/II and to differentiate infertile womenwith endometriosis from infertile women without the condition." (PMID 30969738, 2019). "The FR in females with unexplained infertility was not dependent on number of oocytes, basal FSH, LH and prolactin, neither was dependent on peakE2 and P hormone levels." (PMID 27022334, 2016). "AMH, DHEAS, FSH, LH, PRL, TSH and total testosterone (TT) were prospectively measured in oligo-ovulatory PCOS patients (n = 595) and in ovulatory non-PCOS women (n = 157) referred to a tertiary infertility center." (PMID 27737330, 2016).
pituitary tumor (181 papers, 2005 to 2026). A benign or malignant neoplasm affecting the pituitary gland. "Causes such as pituitary tumor, drug-induced hyperprolactin, sex hormone disorder, and thyroid hormone abnormality eventually act on mammary ducts in the form of elevated prolactin, causing inflammation and increasing the risk of CKC infection." (PMID 39764444, 2024). "Specifically, our data show that after excluding PRL values that are already diagnostic for pituitary tumor-related etiology, PRL levels can predict with modest accuracy the presence of a pituitary lesion, but cannot predict a macrolesion." (PMID 38194218, 2024). "Considering non-pituitary tumors, overall endocrine deficiencies occurred in 51.5 (±26)% for any axis, 22.8 (±17.5)% for prolactin, 20 (±16.2)% for ACTH, 16.2 (±12.8)% for TSH, 20.7 (±11.2)% for FSH/LH and 33.7 (±29.1)% for GH." (PMID 37568636, 2023). "Prolactinomas, the most common type of secretory pituitary tumors, can cause symptoms from prolactin oversecretion, localized mass effects, or both." (PMID 38275385, 2023). "If participants have a continuously raised prolactin level and other causes have been excluded, a pituitary tumor is assumed." (PMID 35098010, 2021). "A prenatally diagnosed familial XLAG case showed a pituitary tumor on MRI already at 3 weeks of age, associated with high prolactin and growth hormone." (PMID 32201880, 2020). "Dopamine agonists (DA) are the most effective treatment for prolactinomas and are a first-line therapy, causing both inhibition of prolactin secretion and pituitary tumor shrinkage." (PMID 33193096, 2020). "It is suggested that long-term exposure to elevated prolactin levels, associated with delayed detection of pituitary tumors, may play an important role in this phenomenon." (PMID 41244055, 2025). "In our study, in addition to patient age, sub-total and gross total resection of the tumor, tumor shape being dumbbell-shaped, irregular, lobulated, PRL subtype, and Ki-67 ≧ 3 were identified as independent risk factors for predicting postoperative recurrence of pituitary tumors." (PMID 40229300, 2025). "The first consisted of patients with a confirmed, previously diagnosed cause of prolactin excess whose plasma prolactin values at initial presentation were >100 ng/mL, exhibited classic signs and symptoms, and underwent imaging studies that identified a pituitary tumor." (PMID 38698869, 2024). "Additionally, ACEIs and AT1R and AT2R inhibitors (losartan and PD 123177, respectively) caused decreased density of PRL-immunoreactive cells and PRL serum levels in estrogen-induced pituitary tumors." (PMID 33673178, 2021). "However, even after controlling for PPAEs, more risperidone-treated patients were tested for prolactin elevation, which is the first, necessary step in the decision pathway leading to diagnostic imaging and subsequent detection of pituitary tumor." (PMID 19210771, 2009). "For long time, routine clinical practice for the management of patients with PRL excess has been based on the assumption that low or undetectable PRL levels during treatment with dopamine agonists might be associated with a better prognosis and long-term rescue from the pituitary tumours." (PMID 39078526, 2024). "Giant prolactinomas are rare pituitary tumors characterized by extremely high prolactin levels and extensive extrasellar invasion." (PMID 42022484, 2026). "Meanwhile, researchers suggested preoperative treatment with bromocriptine for prolactinomas, as it inhibits prolactin secretion and induces tumor shrinkage in most prolactin-secreting pituitary tumors." (PMID 41550875, 2025). "Laboratory examination found increased levels of PRL and transaminase in liver function, and imaging examination indicated pituitary tumor and PH." (PMID 39792764, 2025). "We also identified prolactin-producing pituitary tumors (n = 10, ROR 51.64, PRR 51.63, EBGM05 28.48, IC025 4.71) with positive signal values, albeit in relatively small numbers." (PMID 39833706, 2025).
pituitary tumor (continued). "Pituitary tumors in MEN1 cases show diverse hormonal activity: 60% secrete prolactin, around 25% secrete growth hormone, and 5% secrete corticotropin." (PMID 41155355, 2025). "Noteworthy, unexpected signals not listed in the drug label were also identified, such as psychosexual disorders, prolactin-producing pituitary tumors, suicide attempt, and sudden death." (PMID 39833706, 2025). "Prolactinoma is the most common pituitary tumor, with clinical presentations varying according to sex, age of onset, tumor size, and prolactin (PRL) levels." (PMID 39949381, 2025). "Cabergoline has shown some efficacy in case reports of ACTH-PRL secreting pituitary tumors, with decreases in both PRL and ACTH levels." (PMID 41201503, 2025). "In cases where pituitary tumors and IGM occur together, surgical removal of the pituitary tumor results in a return to normal serum prolactin levels and complete resolution of inflammatory changes in the breast." (PMID 41254701, 2025). "We have recently shown that estrogen‐induced prolactin‐secreting pituitary tumors are aggressive in prenatal alcohol‐exposed female rats." (PMID 41017273, 2025). "For instance, cordycepin has been found to inhibit PRL secretion in rat pituitary tumor cells (GH3) by inducing the expression of cell surface protein ADORA1 and regulating the activation of p-PI3K, p-AKT, p-ERK1/2, and other proteins." (PMID 39199216, 2024). "When pituitary imaging suggests the presence of a pituitary tumor, it should be evaluated if the size of the lesion and the prolactin levels point to the presumptive diagnosis of prolactinoma." (PMID 38578472, 2024). "In pituitary tumors, a notable reduction in E‐cadherin expression has been observed in GH‐PAs compared to PRL‐PAs, as well as in IPAs and clinically recurrent PAs." (PMID 39688352, 2024). "When sellar imaging is suggestive of a pituitary tumor, evaluate if the size of the lesion and prolactin levels point to the presumptive diagnosis of prolactinomas." (PMID 38765533, 2024). "Acromegaly with prolactin-cosecreting pituitary tumors has been found to have a mammotroph-like phenotype, such as a paradoxical GH response to TRH loading and dopamine agonist effectiveness." (PMID 38954291, 2024). "Prolactin co-secretion has been reported in more than 30% of cases, particularly in patients with invasive and extrasellar pituitary tumours, with galactorrhoea reportedly being slightly more frequent in females." (PMID 37891382, 2024). "This evidence has been collected mainly in patients on chronic treatment with dopamine agonists for PRL excess due to a PRL-secreting pituitary tumour, and less frequently in those receiving the atypical antipsychotic aripiprazole." (PMID 39078526, 2024). "Serum prolactin measurement should only be performed in the presence of compatible symptoms and/or in the presence of a pituitary tumor, even with an incidental diagnosis." (PMID 38765533, 2024). "His serum prolactin was 1517 mcg/L (1517 ng/mL; reference range 4-15 mcg/L), and his sellar magnetic resonance imaging showed a 2.0 × 2.2 × 3.1 cm pituitary tumor." (PMID 38660486, 2024). "The second case demonstrated the stability of a noninvasive GH-prolactin co-secreting pituitary tumor after three months of combined treatment with bromocriptine and tamoxifen." (PMID 36950000, 2023). "In a PRL-secreting pituitary tumor cell line, the β-arrestin 2-biased DRD2 ligand UNC9994 induced a stronger reduction in cell proliferation compared to the unselective agonist cabergoline, the currently used drug for this type of tumor." (PMID 37370829, 2023). "While medical therapy is highly effective for most prolactin-secreting pituitary tumors, some cases are resistant to dopamine agonist therapy and are accompanied by hypogonadism persistence, and another treatment modality is required." (PMID 36835974, 2023).
pituitary tumor (continued). "Prolactin normalization is reported in approximately 70–80% of patients, and a decrease in the pituitary tumor size of ~50% occurs in approximately 65% of patients." (PMID 36835974, 2023). "Prolactinomas are the most prevalent subtype of pituitary tumours and are typically characterised by hypersecretion of prolactin (PRL) in the circulating blood suppressing the release of sex steroid hormones." (PMID 36672063, 2023). "Adding to these data, cabergoline, a first-line treatment for lactotroph adenomas, was recently shown to suppress the prolactin hypersecretion and reduce the tumor size via the mTOR inhibition pathway in a rat pituitary tumor." (PMID 37109772, 2023). "It has been shown that Wnt4 was highly expressed in human pituitary tumors expressing GH, PRL, and TSH, all of which belong to the Pit1 cell lineage." (PMID 37109772, 2023). "Thus, GH and PRL dysregulation and pituitary tumor development may have common pathogenic pathways." (PMID 37762304, 2023). "Similar to the previous two genes, TENM1 can also play an important role in different types of cancer especially in the brain tumors such as prolactin pituitary tumor and glioblastoma." (PMID 36193505, 2022). "Pituitary tumors (PT) represent in, the majority of cases, benign tumors for which surgical treatment still remains, except for prolactin-secreting PT, the first-line therapeutic option." (PMID 35207228, 2022). "The first study establishing an involvement of FLNA in pituitary tumor pharmacological resistance was carried out in PRL-secreting tumors." (PMID 37435454, 2022). "Taking into account the presence of a large tumor of the pituitary gland producing PRL, the presence of secondary insufficiency of the adrenal, thyroid glands and gonads, the following diagnosis was made: “Pituitary adenoma (macroprolactinoma)." (PMID 37733390, 2022). "One pituitary tumor from an adolescent patient who harbored a germline heterozygous p.Gln514Pro NF1 variant stained positive for GH and prolactin." (PMID 35456261, 2022). "For example, the individual with infrequent and irregular menses, galactorrhea, elevated prolactin, and a magnetic resonance image demonstrating a pituitary tumor would categorize as a type 2 – N (pituitary neoplasm)." (PMID 35983674, 2022). "This disorder is characterized by early childhood onset gigantism with mixed GH and prolactin-secreting pituitary tumor or hyperplasia before two years of age." (PMID 35456261, 2022). "Estrogen treatment stimulates the secretion of PRL and plays a role in development of PRL-secreting pituitary tumors called prolactinomas." (PMID 33823126, 2021). "Before pregnancy most of the patients with pituitary tumor have the history of irregular menstruation because of the elevated sexual hormones such as prolactin." (PMID 33725898, 2021). "Long-term treatment with pharmacological doses of estrogens induces PRL-secreting pituitary tumors in rodents." (PMID 33823126, 2021). "Firstly, prolactinoma is the most common type of pituitary tumors, which is characterized by excessive prolactin (PRL) secretion as a neuroendocrine-related disease." (PMID 34170848, 2021). "Eventually, we used a new TOPK inhibitor HI-TOPK-032 to explore its function on the proliferation, migration and apoptosis of pituitary tumor cells and its regulation on PRL secretion." (PMID 35126305, 2021). "In this retrospective study, we investigated the prognostic role of galectin-3 and ERα, in predicting aggressiveness, post-surgical outcome, and responsiveness to DA therapy, in patients who underwent first line surgery for PRL-secreting pituitary tumors." (PMID 34322092, 2021). "DA reduces the secretion of prolactin by binding to the dopamine 2 receptor (D2R) in the pituitary tumor, consequently decreasing the tumor volume and lowering the angiogenesis in the surrounding tissue and inducing a tumoricidal effect." (PMID 34771538, 2021).